CD4 (CD4 molecule)
Diseases named in the same sentence as CD4 in open-access papers (continued):
Sharing a sentence is not in itself a finding about the gene and the disease.
tumor (continued). "In the beginning, the high ratio of CD4(+), CD25(+), and regulatory T cell [CD4(+)CD25(+)T(reg)] in all spleen cells and elevated TIM-3 and Foxp3 proteins and mRNA expression levels were observed in the group of spleen cells of tumor-bearing mice." (PMID 37608943, 2023). "Immune cells with high or low Tim-3 expression were intravenously injected into 4T1 tumor-bearing mice, the results showed that the injection of Tim-3+cDC2 exhibited an impaired ability to initiate the production of IFN-γ in CD4+ T cells compared with the injection of Tim-3-cDC2." (PMID 37771774, 2023). "It seems that while both low dose and high dose CYC may have anti-tumor effects, low dose CYC does so through depletion of CD4+CD25+ T-cells and, thus, increased anti-tumor effect, while high dose CYC does so through alkylation and direct cytotoxicity." (PMID 37681925, 2023). "We propose that the sensitivity of tumor cells to the pro-apoptotic activity of IFN-γ is a major determinant of CD4+ CAR T-cell efficacy and may be considered to guide the use of CD4+ T cells during immunotherapy." (PMID 37248395, 2023). "Thus, a 10-fold increase of CD4+/PD-1- T cells and CD8+/PD-1- T cells was recorded in HVEM KO tumor versus HVEM WT tumors, which contrasted with only 3-fold increase in the PD-1+ T cell population for both CD4 T cells and CD8 T cells." (PMID 37033927, 2023). "In contrast to the observed accumulation of CD8 T cells, it hasbeen observed that dysregulation of lipids is associated with a declinein CD4 T cells in the hepatic tissues of mice affected by NASH, bothin the presence and in the absence of tumor development." (PMID 38093838, 2023). "CD4+ T cells, in the presence of TGFβ and IL-10, can differentiate into inducible Treg cells, which are a subset of CD4+ T cells; within different tumors, they suppress antitumor properties of CD4+ and CD8+ T cells leading to poor prognosis and increased tumor growth." (PMID 38139779, 2023). "In the lymphoid compartment, we observed an increase in regulatory T cells (Tregs), decrease in anti-tumor CD8+ T cells in the mammary tissue with little to no change in CD4+ T cells." (PMID 37699010, 2023). "Anti-PD-L1 therapy retarded tumor growth, while CD4+ T cell depletion alone did not significantly affect tumor growth." (PMID 36969495, 2023). "Experiments in traditional 2D systems (i.e., Petri dishes, transwells) revealed that CD4 T cells alone did not kill tumor cells, whereas ML-NK cells killed 85% of patient derived tumor cells in the absence of T cells." (PMID 37865647, 2023). "In HCC, CD4 + effector memory T (Tem) cells and Tregs progressively grow in number from the adjacent non-tumor region to the leading-edge area (slightly) to the tumor core (significantly), whereas CD8 + Tem cells showed the opposite trend." (PMID 36773210, 2023). "Consequently, high quantities of tumour-infiltrating CD8+ T cells, and of cells that stimulate their function (e.g. CD4+ T cells, conventional type 1 dendritic cells, and B cells), are generally associated with relatively good prognoses." (PMID 37936700, 2023). "Taken together, our study demonstrates a critical role of human CD4 CTLs in mediating tumor clearance independent of CD8 T cells and provides a platform to study human anti-tumor immunity in vivo." (PMID 37185301, 2023). "Tumor cells presenting or releasing tumor antigens are engulfed by antigen presenting cells (APCs), which process tumor antigens and present MHC-I and MHC-II molecular complexes to CD8+ T-cell and CD4+ T-cell receptors then accurately identify cancer cells." (PMID 36911712, 2023). "Vaccination of HLA-transgenic mice with homocitrullinated peptides stimulates potent anti-tumour immunity that is CD4 T cell dependent and provides survival benefits with no related toxicity." (PMID 38567060, 2023).
tumor (continued). "However, when we combined the central tumor slide area and invasive border slide, we did see relatively more M2 compared to CD8+ T cells and more CD4+ compared to CD8+ T cells in the tumor tissue compared to the adjacent tissue." (PMID 37938368, 2023). "The significant difference in the number of CD4 + CD25 + FOXP3 + Tcells in the lymph node and tumor tissues was found in the population of the EPA and gp100 monotherapy groups compared to the combination therapy groups EPA + gp100 and Lip-EPA + Lip-gp100 (p < 0.0001)." (PMID 37037839, 2023). "Compared with Ero1aWT counterparts, tumors from mice bearing Ero1aKO MC-38 cells exhibited a higher abundance of tumor-infiltrating CD4+ T, CD8+ T, and natural killer (NK) cells but not regulatory T cells (Tregs), macrophages, or MDSCs." (PMID 37769655, 2023). "Moreover, the Th1 profile induced by the OMVs favored the migration of IFN‐γ‐producing CD4+ and CD8+ T cells to the tumor site, essential to the protective activity of the vaccine." (PMID 37357142, 2023). "So, we can summarize that CD4+ T cells are significant for the differentiation, effector function, antitumor of CD8+ T cells in TME, and it might be important for tumor immunotherapies." (PMID 38082437, 2023). "Moreover, the functions of CD4+ T cells are not only to activate more CD8+ T cells and B cells to kill tumor cells, but also to directly kill tumor cells through recognizing cancer antigens presented by MHC class II and releasing cytotoxic cytokines." (PMID 36986491, 2023). "Through activating antitumor immune cells and regulating the percentages of CD3+, CD4+, CD8+ T cells and CD19 B cells in tumor-bearing mice, APS have been found to be practical as a supplement for immune enhancement that can promote anaerobic metabolism of the TME and cell apoptosis." (PMID 37741920, 2023). "Interestingly, the number of CD8+ Vβ3 T cells decreased in the tumors following C4, while CD4+ T-cell numbers remained stable, possibly due to cell death of the CD8+ Vβ3 T cells in the TME following serial activation and tumor engagement." (PMID 36967382, 2023). "As our depletion studies have shown, both CD4+ and CD8+ T cells are necessary for tumor control." (PMID 37087494, 2023). "CD4+ Tregs represent important helper cells involved in tumour growth since they down-regulate the cytotoxic antitumour activity of CD8+ T cells, and their presence within a tumour correlates with a poor prognosis in different cancer types." (PMID 39698297, 2023). "DC have MHC class I and II molecules on their surface, which when combined with antigenic peptides trigger CD4+ helper T cells (Th) and CD8+ cytotoxic T lymphocytes (CTL) to elicit specific anti-tumour cellular and humoral immunity, inhibiting tumour cell growth." (PMID 37304305, 2023). "Tumor-specific CD4+ T cells can support therapeutic effects by maintaining effector CD8+ T cells, which are important to reduce the exhaustion of CD8+ T cells mediated by PD-1 and TRAIL-mediated apoptosis during initial tumor elimination." (PMID 38060103, 2023). "T cells are an important part of the immune system and can be divided into two categories according to their function in tumour development: CD4+ helper T cells (Th cells) and CD8+ T cells, which play an anti-tumour role, and Treg cells, which play a pro-tumour role." (PMID 38259489, 2023). "This leads to activate of effector CD4 and CD8 + cytotoxic T cells for effective tumor response." (PMID 36411943, 2023). "This phenomenon was independent of cytotoxic T-cells, indicating that pro-tumor activity of CD4+ T-cells did not involve the suppression of CTLs." (PMID 37835465, 2023). "Our studies revealed that combination therapy further inhibited the proportion of MDSCs in the spleen and blood and reprogrammed them into a more mature phenotype, ultimately leading to the promotion of the differentiation of Th1-dominant CD4+ T cells and enhancing CD8+ T-mediated tumor killing." (PMID 37108179, 2023).
tumor (continued). "Moreover, since DCs play an important role in delivering help signals from CD4+ T cells, DC‐based vaccines and the CD27 agonism have recently been exploited to inhibit tumor growth." (PMID 37829505, 2023). "In conclusion, these observations indicated that CD10 and Tfh markers highlighted the source of origin of this tumor cell which resides among non-neoplastic reactive T cells (CD4+ and CD8+) in the TME of AITL." (PMID 37746258, 2023). "Moreover, an immunohistochemical analysis indicated that the recombinant PRV effectively increased the infiltration of CD4+T and CD8+T cells and enhanced the anti-tumor immune response of the organism in vivo." (PMID 37513021, 2023). "Tumor infiltrating leukocytes, particularly monocytes, myeloid derived suppressor cells (MDSCs) and neutrophils create a tumor microenvironment (TME) that is inhospitable to effector cells such as CD4 and CD8 T cells and NK cells." (PMID 37114134, 2023). "lnc-EGFR was found to induce naive CD4+ T cell precursors to differentiate into Tregs, and the overexpressed lnc-EGFR increased the percentage of Tregs infiltrating in hepatocellular carcinoma and promoted the growth of the tumor." (PMID 37637063, 2023). "In aggregate, these data suggest that NEC immunization confers anti-tumor restriction through CD4+ T cells and independent of CD8+ T cells." (PMID 38196632, 2023). "Statistical analysis indicated that tumor-positive lymph nodes had higher frequencies of CD4+ TSCM and TCM than lymph nodes without tumors." (PMID 37835465, 2023). "L. polysaccharides could inhibit tumor growth as a result of CD4+ and CD8+ activation; the upregulation of tumor-suppressing cytokines, including IL 2, IL 6, and IL 7; and the downregulation of TNFα." (PMID 37836809, 2023). "CD4+ T lymphocytes can activate CD8+ T lymphocytes and promote the secretion of cytotoxic granules to kill tumor cells by modulating antigen presenting cells(APC) to provide stronger antigenic signals, or by providing co-stimulatory signals via dendritic cells." (PMID 37206348, 2023). "Because the antigen recognition domain of NHS76 is directed against areas of necrosis, and is therefore tumor targeted, we observed enhanced NHS-IL-12 retention in the TME, resulting in improved antitumor immunity, and increased infiltration of CD4+ and CD8+ T cells." (PMID 37166485, 2023). "Meanwhile, mice who were immunized with pCT26-5 and then late depleted of their CD4+ T cells in this experiment showed the similar capacity to control tumor growth as pCT26-5 non-depleted (isotype control) mice." (PMID 37244905, 2023). "By contrast CD4 depletion does not impact the initial tumor antigen-specific CD8 T cell response in the peripheral blood or the ability to form CD103+ CD8 T cell populations in the tumor." (PMID 37072485, 2023). "Moreover, CTLA-4 expression on conventional CD4+(CD8−)CD25+FOXP3+ Tregs was substantially downregulated by SDT – by two-fold in both target and off-target tumours (large effect size for both)." (PMID 36319895, 2023). "For example, one study found that cryo-thermal therapy, but not RFA, led to a strong neoantigen-specific CD4+ T-cell response that mediated the resistance to tumor challenge." (PMID 37251920, 2023). "Upon stimulation with CLTCH129>Q peptide-pulsed splenocytes in vitro, CD4+ T cells expressing TCR 1 upregulated CD40L, suggesting that this mechanism may be responsible for protection from tumor challenge." (PMID 37400675, 2023). "Antibody-mediated depletion of CD8+ T cells or CD4+ T cells—but not of neutrophils—abrogated the time-of-day-dependent differences in tumour size." (PMID 36470303, 2023). "Additionally, the combination treatment increased the ratios of CD4+ T, CD8+ T, and NK cells from the spleen in tumor-bearing mice." (PMID 37640735, 2023).
tumor (continued). "We also examined whether CD4 T cells from TCF-1 cKO mice might impact the T-box transcription factor family members Eomes and T-bet, which are important in anti-tumor responses of T cells and play central roles in T cell mediated GvHD and alloimmunity." (PMID 36901757, 2023). "In vivo, GCDs decreased tumor growth without apparent organ toxicity and promoted CD4+ T cell infiltration in the tumor." (PMID 36969027, 2023). "Notably, EB1 knockdown completely abolished l-fuc-triggered tumor suppression and induction of total itICs, including DC, CD8+ and CD4+ T cell subpopulations, similar to the effects elicited by CD4+ T cell depletion." (PMID 36690875, 2023). "Moreover, during the evaluation of the therapeutic effect on distant tumors in a bilateral tumor model, overexpression of CD3+ CD8+ and CD3+ CD4+ T cells in the blood, as well as the downregulation of MDSCs, resulted in substantial abscopal effects." (PMID 36987269, 2023). "Moreover, the presence of Tregs and MDSCs has a significant suppressive role by inhibiting effector T cell activities and reducing CD4+ T cells and effector CD8+ T cells anti-tumor activation." (PMID 36672682, 2023). "Mirroring the conditions during tumor initiation, low number of CSCs could successfully generate CD4+CD25+FOXP3+ Treg cells from infiltrating CD4+ T lymphocytes in a contact-independent manner." (PMID 38038865, 2023). "Notably, tumor immune‐related cytokines, including tumor necrosis factor (TNF)‐α, IL‐1β, IL‐2, IL‐6, IL‐17, CD4+/CD8+, IFN‐α, and IFN‐γ, were determined." (PMID 36951443, 2023). "Moreover, TGF-β promotes the differentiation of CD4+CD25- T cells into Tregs, which further prevents immune activation and anti-tumor immunity in response to a presented tumor neoantigen." (PMID 38275827, 2023). "We also did not observe increased frequencies of tumor infiltrating CD4+, CD8+ and NK cells following ACC treatment." (PMID 36911698, 2023). "Similarly, adagrasib decreased intertumoral immunosuppressive myeloid-derived suppressor cells and M2-polarised macrophages and increased immune-promoting M1-polarised macrophages, dendritic cells, CD4+ cells, and NKT cells in KRAS G12C tumours." (PMID 36980522, 2023). "Moreover, we further analyzed the correlation between CCNE1 expression and tumor purity, B cell, CD8 + cell, CD4 + cell, macrophage, neutrophil and dendritic cell (DC) in UCSC, LUSC, SARC and STAD via the TIMER portal." (PMID 36964635, 2023). "Immunohistochemical staining for CD4+ and CD8+ T cells showed remarkably increased numbers of CD4+ and CD8+ T cells infiltrating into the tumor tissues in mice treated with the combination of B. longum 420 and anti-PD-1 antibody compared to the other treatment groups." (PMID 37340017, 2023). "We indeed observed that low-dose Lipo-MP-LPS was not able to induce the activation of T-cell responses in periphery and thus tumor infiltration by CD4/CD8 T-cells, which can be related to its lack of efficacy to fully differentiate TAMs toward an M1 phenotype." (PMID 37760603, 2023). "Furthermore, both CD4+ and CD8+ T cells with anti-tumour functionality (particularly IFN-γ and TNF co-production) are enriched within the PD-1+ fraction of MC38 TILs." (PMID 37153625, 2023). "Moreover, CMS5 tumors proceeded more aggressively when lacking CD4+ T or CD8+ T cells in the control groups, suggesting that CD4+, CD8+, or both T cells are essential in suppressing tumor growth." (PMID 37407600, 2023). "These subsets of CD4+ T cells produce a variety of cytokines that modulate inflammatory responses and activate gene programs in CD8+ T cells, thereby enhancing their anti-tumor response." (PMID 38213535, 2023). "Interestingly, these cells not only exhibited strong anti-tumor reactivity and potent proliferative capacity of αβ T cells, leading to tumor eradication in leukemic PDX models, they also retained both CD4+ and CD8+ effector cell functions." (PMID 37426670, 2023).
tumor (continued). "Overall, in physiological conditions, mature CD4+ and CD8+ SP thymocytes exit the thymus to populate the peripheral lymphoid organs and participate in adaptive immune responses, including those underpinning anti-tumor immunity." (PMID 37529610, 2023). "However, effector CD4+ T helper cells can promote cytotoxic CD8+ T cell function via activation of DCs and regulate the myeloid compartment and tumor cells via secretion of immunomodulatory factors such as IFN-γ and TNF-α." (PMID 36719372, 2023). "Consistent with the change in circulating immune cell counts, there was no significant change in immune cell count or the CD4+/CD8+ ratio in periablational tumor tissues after 30 min of treatment with iRFA (p > 0.05)." (PMID 37231509, 2023). "When we used anti-NK1.1 to deplete NK cells from our model, HCC development was promoted in Chatfl/fl mice but not in Chatfl/fl; Cd4-cre mice, essentially eliminating the differences in tumor progression." (PMID 37640929, 2023). "For example, antigen presentation to CD4+ and CD8+ T helper and cytotoxic T cells may facilitate an adaptive immune response against tumor neoantigens." (PMID 37373873, 2023). "Moreover, the levels of CD4 and CD8 positive cells in tumor tissues were notably elevated by overexpression of METTL16 and anti-PD-1 treatment compared with the control group and were further increased by their combination." (PMID 37647025, 2023). "Furthermore, we found that CD4+ and CD8+ T cells were evenly distributed in tumor samples compared with the normal group." (PMID 37889543, 2023). "T cells with effector memory phenotypes, CD4+ TFH cells, B cells with antigen-presenting function, antibody-producing plasma cells, and memory B cells are all generated within TLSs, and play a significant role in anti-tumor immunity." (PMID 37868967, 2023). "CD4+ T cells are also suitable for ACT because they support antigen presentation from DCs, T cell homing through the secretion of chemokines such as CXCL9-11, formation of CD8+ T cell memory, and direct tumor elimination by granzymes, perforin, TRAIL, or FasL." (PMID 37970489, 2023). "Furthermore, C26 tumor-bearing mice displayed a significant decrease of PD-L1-positive macrophages and g-MDSC in the blood, and an increase of PD-1-expressing CD4+ and CD8+ T cells and of PD-L1+ m-MDSC in the spleen, again regardless of FK506 administration." (PMID 38052214, 2023). "Moreover, the levels of interferon by natural killer (NK) and T helper type 1 (Th1) CD4+, CD8+ cells limit tumor progression by activating cytotoxic immunity, and the presence of Th1 polarization markers correlate with lower tumor recurrence in CRC patients." (PMID 38096329, 2023). "Interestingly, depletion of ICBs and Tregs promotes vascular normalization by reducing tumor vascular density and reactivating IFNγ producers (i.e., CD8+/CD4+ effector T cells), which IFNγ has the potential to limit tumor angiogenesis." (PMID 37727791, 2023). "This promoted the adaptive immune response mediated by CD4+ T cells and CD8+ T cells in the “cold” tumor, enhancing the immunogenicity of the tumor site and converting it from a “cold” to “hot” tumor for superior tumor‐killing effect." (PMID 37884486, 2023). "Specifically, Fap2 binds to a T-cell immunoreceptor with Ig and immunoreceptor tyrosine-based inhibitory motif domains (TIGIT) and impairs the function of CD4+ T, CD8+ T, and NK cells; moreover, it reduces cytotoxicity, resulting in tumor escape from immunosurveillance." (PMID 37819098, 2023). "The retention of occult tumor cells is facilitated by IL-12, IFN-, CD4+, and CD8+ T cells." (PMID 37759229, 2023). "LRP1B expression in TCs stimulates the infiltration of CD4+ and CD8+ T cells and raises the ratio of CD86/CD163, which may be due to an increase in tumor immunogenicity to achieve immune activation and prevent disease progression." (PMID 38136305, 2023).